MET (MET proto-oncogene, receptor tyrosine kinase)
Diseases named in the same sentence as MET in open-access papers (continued):
Sharing a sentence is not in itself a finding about the gene and the disease.
glioma (continued). "It has been shown that HGF/MET signaling can promote growth and migration of gliomas cells via up-regulating COX-2 expression and stimulating the release of PGE2." (PMID 35935338, 2022). "Much of the literature discussing the role of HGF/c-MET in glioma is based upon studies of adult primary tumors, or cell lines derived from adult tumors." (PMID 36034555, 2022). "Crizotinib can also effectively inhibit the survival and proliferation of MET-positive glioma stem cells, meanwhile, and can prolong survival of mice with MET-positive GSCs." (PMID 35935338, 2022). "HGF/MET interaction is frequently committed in human gliomas and high levels of these molecules correlate with high tumor grade and poor prognosis." (PMID 35069735, 2022). "The HGF/c-MET pathway has been shown to contribute to anti-cancer therapy resistance in human gliomas." (PMID 36034555, 2022). "Hepatocyte growth factor receptor (c-MET) signaling has a role in gliomagenesis and glioma stem cell (GSC) maintenance." (PMID 35625997, 2022). "To further illustrate the mechanism of MET hyperactivation in gliomas harboring ZM fusions, we analyzed the protein structure of the partner fragment of MET (the PTPRZ1 fragment) in PTPRZ1‐MET." (PMID 33645009, 2021). "For example, the oncogene MET was amplified with 5.1% cases while overexpressed in 13.1% cases of glioma." (PMID 34253710, 2021). "According to the remarkable role of ZM as a driver of glioma progression and indicator of MET inhibitor sensitivity, it is necessary to detect this alteration even when it presents in glioma with relatively fewer copies." (PMID 33645009, 2021). "In the PDGFRA#4 case, MET overexpression was most likely caused by the presence of a PTPRZ1-MET fusion, as PTPRZ1 is among the highest expressed genes in glioma, and the fusion places MET under the control of the PTPRZ1 promoter." (PMID 34572759, 2021). "In gliomas, the activation of MET promotes the proliferation of tumour and reduces cell death induced by cisplatin, taxol, and gamma irradiation." (PMID 34205437, 2021). "c-MET expression abrogation by epigenetic silencing in glioma cells suppresses Akt pathway activation and up-regulates the expression of the autophagy-related protein Atg5, resulting in tumor growth reduction." (PMID 34178638, 2021). "As the repressive effects of MET inhibitor in malignant progression of ZM+ glioma had emerged, the early detection of these alterations will benefit the patients in prevention or early management." (PMID 33645009, 2021). "The human RTK family has 58 known members; these are further classified into 20 multi-member subfamilies including EGFR, VEGFR, PDGFR, FGFR, and MET, which are the most commonly studied RTKs in glioma initiation and progression." (PMID 34806012, 2021). "These clinical findings indicate a clinical potential for precisely treating gliomas by targeting MET fusions." (PMID 34671307, 2021). "A potential mechanism involved in spontaneous differentiation of gliomas harboring ALK/ROS1/NTRK/MET alterations is oncogene-induced senescence." (PMID 34704035, 2021). "Inhibition of SF/HGF and c-met expression anti-SF and anti-c-MET U1/ribozymes promotes tumor cell apoptosis and inhibits tumor angiogenesis in an in vivo glioma model." (PMID 32152825, 2020). "For signaling pathways genes, the expression of CXCR4, BIRC5, CTNNB1, FZD4, and MET were significantly increased in high-grade gliomas." (PMID 32154177, 2020). "COL1A1 has been shown to be involved in cell invasion, and MET is an important factor involved in a variety of processes that contribute to the malignancy of gliomas." (PMID 32604718, 2020). "For instance, BRAF 35, EGFR 36, EZH2 37, MET 38 and mTOR 39 have been reported as potential protein targets for glioma treatment." (PMID 31523189, 2019).
glioma (continued). "In other words, MET overexpression in this glioma with the G-CIMP-demethylated (C3) profile was possibly driven by the active MKLN1 promoter created by gene fusion, which led to activation of mitogen-activated protein kinase (MAPK) signaling." (PMID 30760837, 2019). "Pair-wise comparison of CNAs in the glioma-associated genes ALK, PDGFRA, VEGFR2/KDR, EGFR, MET and FGFR1 was performed employing MLPA techniques." (PMID 30894200, 2019). "A novel MET fusion was identified in an IDH-mutant recurrent glioma (MT 60-2) in the G-CIMP-demethylated (C.3) group with RNA-seq and was confirmed with direct sequencing following PCR amplification of the cDNA." (PMID 30760837, 2019). "Nevertheless, our results show that LRIG1 suppresses the migration of glioma cells in a cell context-dependent manner partially via MET inhibition." (PMID 29391393, 2018). "In summary, Lrig1 is a haploinsufficient suppressor of PDGFB-driven glioma, possibly in part via negative regulation of MET-driven cell migration and invasion." (PMID 29391393, 2018). "c-MET is also overexpressed in human glioblastomas, and expression levels correlate with glioma malignancy grade and vascularity, promoting glioma growth and angiogenesis in vivo." (PMID 28404966, 2017). "In 2008, the team successfully visualized overexpressed c-MET in C6 (rat glioma) rat models in vivo by MRI based on a targeting contrast agent, anti-c-MET-Gd-DTPA-albumin, an anti-c-MET antibody linked to biotinylated Gd-DTPA-albumin." (PMID 28485003, 2017). "In 2010, Towner and colleagues reported another novel MRI molecular imaging probe for the in vivo detection of c-MET overexpression in C6 rat glioma models." (PMID 28485003, 2017). "RAS/MAPK activation in glioma has been shown to result both from constitutive activation of receptor tyrosine kinases EGFR, PDGFRA, and c-MET as well by an inactivating mutation of NF1, a suppressor of RAS GTPase activity." (PMID 28256619, 2017). "TAMs are enriched in the RMPAhigh gliomas and they show high surface expression of MET, VEGFR1, KDR, EPHB4 and NRP1." (PMID 27385209, 2016). "The most characterized HGF-dependent xenograft model is the U87-MG human glioma cells, which expresses both human MET and HGF29." (PMID 27546726, 2016). "In these RMPAhigh gliomas, angiogenic related RTKs including MET, VEGFR1, KDR, EPHB4, NRP1 were frequently and concomitantly expressed in CD45+ immune cells and CD105+ endothelial cells." (PMID 27385209, 2016). "For example, previous studies have suggested co-activation of RTKs including EGFR and MET in GBM samples, we also see high MET expression in RMPAhigh gliomas, with about 5% of the RMPAhigh gliomas harboring MET amplification." (PMID 27385209, 2016). "In contrast, clustering pre- and post-treatment of DBM2 and U251M2 glioma lines was less tight between vehicle and treated tumors indicating that MET inhibition had a global effect on gene expression profiles of these models." (PMID 26381735, 2015). "Some genes in this survival module were similarly implicated in the occurrence and development of glioma, such as ERBB2, ITGB3, EGFR, and MET." (PMID 24809850, 2014). "Together with ErbB and PDGFR family members, MET represents one of the oncogenic drivers in glioma tumor biology." (PMID 25238264, 2014). "The HGF/c-MET axis is important in both angiogenesis and cell migration in several tumor types including glioma." (PMID 23484006, 2013). "HGF is a strong stimulator of in vitro glioma cell migration and c-MET expression has also been demonstrated in invasive glioma cells." (PMID 23484006, 2013). "Prior reports have shown that miR-34a is downregulated in GBM compared to normal brain, and that it inhibits cell proliferation, survival, and invasion in adherent glioma cell lines by targeting MET, NOTCH1, NOTCH2, and CDK6." (PMID 22479456, 2012). "LMH 87 also reduced total c-MET by 50% in U87MG glioma cells, as determined by densitometry (bar graph)." (PMID 22511956, 2012).
glioma (continued). "Next, we sought to correlate the presence of autocrine driven HGF/c-MET complexes in glioma cells with a direct indicator of c-MET activation." (PMID 21283737, 2011). "We measured c-MET pY1003 levels by immuno-precipitation in lysates prepared from the Ln18, Ln229, U118, U138, and U87MG glioma cell lines to compare with the HGF/c-MET levels we detected using the VeraTag FFPE assay format." (PMID 21283737, 2011). "In several glioma cells that exhibit activation of HGF/c-MET signaling, we detected high levels of c-MET (pY1003) phosphorylation that are likely modulated through a c-MET and HGF autocrine loop." (PMID 21283737, 2011). "The MET gene is also one of the druggable genes in high‐grade gliomas." (PMID 41521799, 2026). "The MET gene is one of the druggable genes in high‐grade gliomas." (PMID 41521799, 2026). "To investigate this hypothesis, we used flow cytometry to isolate one population of MET+, F4/80− and one population of MET−, F4/80− cells as a control from glioma tissue and expanded these cells in culture." (PMID 41339360, 2025). "Additionally, glioma cells create drug delivery barriers via paracrine HGF/MET‐induced endothelial remodeling, providing a rationale for nanocarrier‐based co‐delivery systems." (PMID 40654157, 2025). "MET inhibitors show promise for a wider range of applications in gliomas with MET alterations." (PMID 40469416, 2025). "MET is frequently over-expressed in human GBM due to amplification, mutation, and fusion events and has been demonstrated to promote tumorigenesis through stimulation of glioma cell migration and invasion." (PMID 41339360, 2025). "This may be supported by the previous observation of a strong MAPK activation due to MET overexpression in a MET fusion-positive pediatric glioma in vitro model." (PMID 38902810, 2024). "Overexpression of MET has been found in tissues derived from glioma patients." (PMID 38115126, 2023). "Moreover, the exploration of various molecular targets, such as EGFR, EGFRvIII, miRNAs, MET, and other signaling pathways, underscores the complex nature of glioma and the potential for targeted therapies." (PMID 38002561, 2023). "However, the effect of MET genes on primary gliomas, specifically GBM, and their ability to evade immunosurveillance checkpoints is not well understood." (PMID 38077251, 2023). "Gliomas with BRAF gains commonly had concomitant gains in MET, SMO, EZH2, and CDK6 (p < 0.001 each), along with other genes on 7q, which may reflect larger chromosomal duplications." (PMID 36854806, 2023). "Notably, hepatocyte growth factor receptor tyrosine kinase MET shows a strong gain of interaction with CPD in glioma." (PMID 35768873, 2022). "Notably the single patient with a MET translocation (glioma) had progressive disease with crizotinib therapy." (PMID 36034555, 2022). "In addition to autocrine HGF, paracrine HGF can also promote the invasion of glioma and enhance the chemotactic invasion and proliferation of the MET-positive cells." (PMID 35935338, 2022). "Furthermore, in high-grade glioma, MET levels are higher and miR-410 levels are lower, while low-grade gliomas are characterized by higher levels of miR-410 which decreases MET expression." (PMID 35069735, 2022). "The authors concluded that miR-410 directly targets 3’-UTR of MET mRNA and may affect high-grade glioma cell proliferation and invasion through MET regulated AKT signaling." (PMID 35646622, 2022). "It has been reported that HGF and MET were highly expressed in glioma to promote tumor growth and angiogenesis, which could also boost tumor evolution and malignant progression to HGG by activating AKT and MAPK pathways." (PMID 35677036, 2022). "Indeed, irradiation of glioma stem cells has been shown to induce c-MET upregulation, while in vitro studies have shown that pre-treating GBM cells with HGF reduced the cytotoxic effect of DNA damaging agents." (PMID 36034555, 2022).
glioma (continued). "ZM fusions are critical drivers of glioma progression and effective target of MET inhibitor." (PMID 33645009, 2021). "Overexpression of HGF/MET axis leads to glioma formation in mice." (PMID 34806012, 2021). "Besides, as a MET‐dependent glioma cell line,31 U87 MG was widely used in MET signaling pathway‐related researches." (PMID 33645009, 2021). "The hyperactivations of MET signaling driving glioma progression might be contributed by a ligand‐independent activation enabled by the protein structure modification of extracellular domain of MET in ZM fusions." (PMID 33645009, 2021). "In glioma cells, irradiation induces ligand‐independent overexpression and activation of MET." (PMID 32133617, 2020). "Furthermore, miR-410 was down-regulated in human glioma tissues, acting as a tumor suppressor to greatly affect glioma growth by down-regulating its target gene MET." (PMID 30498093, 2019). "FBS stimulation of C6 glioma cells led to phosphorylation of MET, EGFR, AKT, and ERK1/2." (PMID 31595389, 2019). "The oncogenes EGFR and c-MET were co-expressed in approximately 41% of these gliomas." (PMID 29621254, 2018). "Amplification of MET and its ligand HGF has been associated with primary and lower-grade gliomas." (PMID 28458684, 2017). "MET expression in the CD45−CD105− cells was detected in 1 of the 6 RMPAhigh gliomas analyzed." (PMID 27385209, 2016). "Our data suggest that although MET inhibitors have consequences on distinct molecular processes on subcutaneous glioma tumor cells and host cells within the tumor (endothelial cells, macrophages, stromal elements, etc.), V-4084 affects cell cycle in both tumor and host." (PMID 26381735, 2015). "Further, it has been shown that in GBM cells, EGFRvIII transactivates other RTKs, including the hepatocyte growth factor (HGF) receptor (MET) and co-targeting of these RTKs has a potent antitumor efficacy, thus suggesting a potential strategy for treating EGFRvIII-expressing gliomas." (PMID 26461476, 2015). "MET inhibitors appear to lead to aberrant MET amplification in gliomas." (PMID 23516171, 2013). "In conclusion, cabozantinib is a promising therapy for c-MET positive glioma, but improving delivery of the drug to the tumor and/or the surrounding tissue may be needed for full activity." (PMID 23484006, 2013). "Elevated expression of c-MET in glioma specimens has been documented by several groups." (PMID 23484006, 2013). "U87MG glioma cells are dependent on the HGF/SF:c-MET signaling axis for in vivo growth." (PMID 22511956, 2012). "In addition, detection of endogenous levels of HGF/c-MET in glioma cells was consistent between proximity FFPE and SPPICE biochemical assays." (PMID 21283737, 2011). "Furthermore, HGF-c-MET activation in glioma cell lines was verified by Surface Protein-Protein Interaction by Crosslinking ELISA (SPPICE) assay in corresponding soluble cell lysates." (PMID 21283737, 2011). "Next, we evaluated whether the FFPE assay could be used to detect endogenous levels of HGF/c-MET complexes in glioma cell lines that activate c-MET signaling through the autocrine production of HGF." (PMID 21283737, 2011). "Finally, our further mechanism exploration revealed that c-MET might play a vital role in the interaction between disulfidptosis and glioma immunity." (PMID 38352883, 2024). "As the detection of a recurrent TRIM24::MET fusion expands the spectrum of known driving fusion genes in infant-type hemispheric glioma, this comparative illustration may indicate a notable clinico-pathological heterogeneity of tumors bearing this particular molecular driver alteration." (PMID 38902810, 2024). "Moreover, MET-deficient GL-261 glioma cells had no growth disadvantage as determined by measures of cell doubling time, viability or cell cycle progression in vitro." (PMID 36915128, 2023). "Glioma patients harboring ZM could benefit from MET inhibitors." (PMID 33645009, 2021).
glioma (continued). "Also, MET overexpression could significantly abrogate miR-410 dependent effects on glioma proliferation and invasion." (PMID 32083078, 2020). "Therefore, even though MET expression was low in most samples, the fusion gene that may produce the MET protein was highly expressed in this recurrent glioma." (PMID 30760837, 2019). "Likewise, treating GBM patients with MET inhibitors after surgical debulking may enhance the efficacy of adjuvant radiation and chemotherapy by arresting the invading glioma cells." (PMID 26381735, 2015). "Because HGF-autocrine activation is the key molecular feature determining responsiveness to MET inhibitors, we asked whether sensitive glioma subcutaneous xenografts are transcriptionally similar to each other and are dissimilar from insensitive glioma models." (PMID 26381735, 2015). "Some gliomas may be dependent on MET amplification and therefore respond to MET inhibitors." (PMID 24213322, 2012). "The MET proto-oncogene, located on chromosome 7q31, and HGF, located on chromosome 7q21.1, are crucial in glioma cell biology, affecting tumor proliferation, growth, migration, invasion, angiogenesis, and stemness." (PMID 40332008, 2025). "These include “diffuse midline gliomas (H3 K27-altered)”, “diffuse hemispheric gliomas (H3 G34-mutant)”, “diffuse pediatric-type high-grade gliomas (H3-wildtype and IDH-wildtype)” and “infant type hemispheric gliomas (ALK, MET, NTRK 1/2/3 or ROS1 fusion)”." (PMID 38525424, 2024). "Infant-type hemispheric glioma is commonly initiated by a fusion event involving a receptor tyrosine kinase (RTK) gene, such as NTRK1/2/3, ALK, ROS1, or MET." (PMID 39273062, 2024). "Many potential candidates were screened, among which c-MET was validated for its TDG and immune regulation roles (inducing t-cell exhaustion) in glioma." (PMID 38352883, 2024). "Oncogenic fusions with receptor tyrosine kinase (RTK) genes NTRK, ALK, ROS or MET drive a subgroup of pHGG in infants (IHG, Infant-type hemispheric glioma)." (PMID 38849845, 2024). "Among them, c-MET was validated as a tumor driver gene and JAK3-STAT3-PD-L1/PD1 regulator in glioma and T cells." (PMID 38352883, 2024). "IHC glioma marker panel (SOX2, Tubulin, beta-3, EGFR, A2B5, and c-MET).FISH used to determine EGFR gene amplification in CTCs from known amplified cases." (PMID 38481938, 2024). "The RNA sequencing analysis of 140 samples of the two cohorts ‘gliomas and BM revealed samples with gene rearrangements that involve NTRK3, FGFR3, ERG, EGFR, or MET genes in seven samples (5%)." (PMID 39087020, 2024). "Occurring in newborns and infants, these glial tumors are characterized by a distinct molecular profile driven by kinase fusion genes involving the NTRK family, ALK, ROS1 or MET." (PMID 38902810, 2024). "We find that the murine glioma cell lines GL-261, SMA-497, SMA-540 and SMA-560 express HGF and its receptor MET and respond to exogenous HGF with MET phosphorylation." (PMID 36915128, 2023). "Alterations in CDK4/6, CIC, FGFR2/3/4, FUBP1, KIT, MET, NF1, PEG3, RB1, and NTRK2 were additional factors correlated with the survival of different subtypes of gliomas." (PMID 36998447, 2023). "Accordingly, targeting MET by gene silencing potentiated responses to irradiation in the human U87MG and U251 intracranial glioma xenograft models." (PMID 36915128, 2023). "We first examined HGF and MET expression levels and constitutive MET activation in the GL-261, SMA-497, SMA-540 or SMA-560 mouse glioma models." (PMID 36915128, 2023).